TRIM27 (tripartite motif containing 27)
Description:
E3 ubiquitin-protein ligase that mediates ubiquitination of various substrates and thereby plays a role in diffent processes including proliferation, innate immunity, apoptosis, immune response or autophagy. Ubiquitinates PIK3C2B and inhibits its activity by mediating the formation of 'Lys-48'-linked polyubiquitin chains; the function inhibits CD4 T-cell activation. Acts as a regulator of retrograde transport: together with MAGEL2, mediates the formation of 'Lys-63'-linked polyubiquitin chains at 'Lys-220' of WASHC1, leading to promote endosomal F-actin assembly. Has a transcriptional repressor activity by cooperating with EPC1. Induces apoptosis by activating Jun N-terminal kinase and p38 kinase and also increases caspase-3-like activity independently of mitochondrial events. May function in male germ cell development. Has DNA-binding activity and preferentially bound to double-stranded DNA. Forms a complex with and ubiquitinates the ubiquitin-specific protease USP7, which in turn deubiquitinates RIPK1 resulting in the positive regulation of TNF-induced apoptosis. In addition, acts with USP7 or PTPN11 as an inhibitor of the antiviral signaling pathway by promoting kinase TBK1 ubiquitination and degradation. Acts as a negative regulator of NOD2 signaling by mediating ubiquitination of NOD2, promoting its degradation by the proteasome. Alternatively, facilitates mitophagy via stabilization of active TBK1. Negatively regulates autophagy flux under basal conditions by directly polyubiquitinating ULK1. During starvation-induced autophagy, catalyzes non-degradative ubiquitination of the kinase STK38L promoting its activation and phosphorylation of ULK1 leading to its ubiquitination and degradation to restrain the amplitude and duration of autophagy. (Microbial infection) Positively regulates hepatitis C virus replication by suppressing type I IFN response during infection.
Synonyms: RFP; RNF76
Tractability: PROTAC: ubiquitination databases record sites on it; its protein half-life has been measured.
Target class: Enzyme; Transferase
Gene: Protein-coding gene on chromosome 6 (28,903,002 to 28,923,988, reverse strand). Ensembl gene ENSG00000204713.
Subcellular location: Nucleus; Cytoplasm; Nucleus, PML body; Early endosome; Mitochondrion
Subcellular location (Human Protein Atlas): Nucleoli; Nucleoplasm
Pathways (Reactome):
Disease: Suppression of apoptosis
Metabolism of proteins: SUMOylation of ubiquitinylation proteins
Signal Transduction: Regulation of PTEN stability and activity
Gene Ontology:
Molecular function: identical protein binding; phosphatidylinositol 3-kinase inhibitor activity; protein binding; SUMO transferase activity; transcription coactivator activity; ubiquitin protein ligase activity; ubiquitin-protein transferase activity; metal ion binding; nucleic acid binding; zinc ion binding
Biological process: antiviral innate immune response; Arp2/3 complex-mediated actin nucleation; negative regulation of autophagy; negative regulation of gene expression, epigenetic; negative regulation of transcription by RNA polymerase II; negative regulation of type I interferon production; protein K63-linked ubiquitination; regulation of tumor necrosis factor-mediated signaling pathway; retrograde transport, endosome to Golgi; innate immune response; negative regulation of viral transcription; protein sumoylation; spermatogenesis; positive regulation of DNA-templated transcription; protein ubiquitination; suppression of viral release by host
Cellular component: cytoplasm; endosome; mitochondrion; nuclear membrane; nucleoplasm; nucleus; peptidase complex; retromer complex; ubiquitin ligase complex; cytosol; early endosome; PML body
Genetic constraint (gnomAD): Loss-of-function variants: 12 observed, 57.95 expected, observed/expected ratio (o/e) 0.21, 90% interval 0.13 to 0.34. The upper end of that interval is the gene's LOEUF score, 0.34, which puts it in group 1 of 6, group 1 being the genes least tolerant of losing a copy. Missense variants: 403 observed, 671.45 expected, observed/expected ratio (o/e) 0.6, 90% interval 0.55 to 0.65. Synonymous variants: 266 observed, 264.81 expected, observed/expected ratio (o/e) 1, 90% interval 0.91 to 1.11.
Homologues: Orthologues: chimpanzee TRIM27 (100% identical), macaque TRIM27 (100% identical), rabbit TRIM27 (99% identical), dog TRIM27 (99% identical), pig TRIM27 (99% identical), mouse Trim27 (99% identical), rat Trim27 (98% identical), guinea pig TRIM27 (88% identical), tropical clawed frog trim69.2 (28% identical). Paralogues in human: TRIM11 (37% identical), TRIM39 (36% identical), TRIM41 (36% identical), TRIM58 (35% identical), TRIM17 (35% identical), TRIM7 (34% identical), TRIM10 (33% identical), TRIM21 (33% identical), TRIM4 (31% identical), TRIM26 (31% identical), TRIM15 (29% identical), TRIM68 (28% identical), and 68 more.
Diseases named in the same sentence as TRIM27 in open-access papers:
TRIM27 is named in the same sentence as 71 diseases in open-access papers, as found by Europe PMC text mining. Sharing a sentence is not in itself a finding about the gene and the disease. The quoted sentences say what the papers report.
ovarian carcinoma (10 papers, 2019 to 2024). A malignant neoplasm originating from the surface ovarian epithelium. "Abnormal expression of TRIM27 has been observed in various cancers, such as hepatocellular carcinoma, non-small cell lung cancer, ovarian cancer, and breast cancer." (PMID 38911380, 2024). "Upregulation of miRNA-383-5p inhibits cell proliferation and tumor growth, and enhances chemosensitivity of ovarian cancer cells by inhibiting TRIM27 expression." (PMID 37592783, 2023). "At the same time, downregulation of TRIM27 expression inhibited the proliferation of ovarian cancer cells in vivo and in vitro by upregulating the phosphorylation of p38 and downregulating the phosphorylation of AKT." (PMID 36200036, 2022). "Down-regulating the expression of Trim27 can inhibit the proliferation of ovarian cancer cells both in vivo and in vitro." (PMID 35311628, 2022). "Next, we focus on the roles of TRIM27 in cancer, including ovarian cancer, breast cancer and lung cancer." (PMID 36200036, 2022). "Silencing or genetic knockout of TRIM27 ubiquitination-dependently or -independently inhibits malignant biological behavior in breast, colorectal, and ovarian cancers." (PMID 35371994, 2022). "TRIM27 is overexpressed in ovarian cancer tissues and correlated with the unfavorable prognosis of patients with ovarian cancer." (PMID 33066509, 2020). "It was also noticed that miR-383-5p is downregulated in ovarian cancer tissues and is able to target TRIM27." (PMID 33066509, 2020). "Previous studies reported that TRIM27 functioned in an oncogenic role in colorectal cancer and ovarian cancer." (PMID 31921311, 2019). "In ovarian cancer, the expression of TRIM27 was significantly related to metastasis and FIGO stag." (PMID 36200036, 2022). "Trim27 belongs to the Trim protein family, which was reported to take part in several kinds of diseases including colitis, lupus nephritis, diabetes and ovarian cancer." (PMID 35311628, 2022). "Similarly, the TRIM27 transcript level was found to be correlated with ovarian cancer metastasis, and it has been shown that TRIM27 knockdown induces cell cycle arrest by activating the p38 pathway." (PMID 34284744, 2021). "For example, TRIM27 was highly expressed in hepatocellular carcinoma, non-small-cell lung cancer (NSCLC), ovarian cancer and breast cancer." (PMID 36200036, 2022). "Similarly, tumor suppressors miR-136, miR-383-5p, and miR-874 have been reported to conquer PTX resistance of ovarian cancer cells by silencing NOTCH3, tripartite motif containing 27 (TRIM27), and salt inducible kinase 2 (SIK2), respectively." (PMID 34512721, 2021).
breast cancer (8 papers, 2017 to 2024). A primary or metastatic malignant neoplasm involving the breast. "Intriguingly, the frequent presence of TRIM27 overexpression in breast cancer (BC) patients is associated with tumorigenesis, potentially through the inhibition of ULK1-mediated autophagy." (PMID 38803357, 2024). "Previous studies have been demonstrated that TRIM27 was upregulated in several cancers, such as lung, ovarian, germ cell, endometrial, and breast cancers." (PMID 31921311, 2019). "TRIM27 was found to inhibit the apoptosis and senescence of cancer cells in breast cancer." (PMID 36200036, 2022). "For example, TRIM47, TRIM27, UBR5, and FBXW2 can regulate breast cancer progression and endocrine therapy sensitivities via the polyubiquitination of PKC‐ε, P21, β‐catenin, and MSX2, respectively." (PMID 35843886, 2022).
colitis (7 papers, 2018 to 2026). Inflammation of the colon. "The E3 ubiquitin ligase tripartite motif 27 (TRIM27) is a negative regulator of NF-κB activation and the innate immune response, and TRIM27 deficiency significantly impairs dextran sulfate sodium (DSS)-induced colitis." (PMID 42017384, 2026). "We found that Trim27−/− mice displayed attenuated colitis, as determined by less weight loss, higher survival rate, and reduced colon shortening compared to their wild-type littermates." (PMID 30143645, 2018). "Conversely, wild-type mice transplanted with hematopoietic cells from TRIM27-deficient mice (KO > WT) showed decreased susceptibility to colitis as KO > KO mice." (PMID 30143645, 2018). "At the same time, another study demonstrated that TRIM27 could induce colitis to promote the tumorigenesis of colitis-associated cancer by recruiting gp130 and JAK1 to activate the IL6-STAT3 signaling pathway." (PMID 36200036, 2022). "However, TRIM27-deficient mice transplanted with hematopoietic cells from wild-type mice (WT > KO) developed colitis as severe as that of WT > WT mice." (PMID 30143645, 2018). "In addition, our results suggest hematopoietic cells are responsible for attenuation of DSS-induced colitis in TRIM27-deficient mice." (PMID 30143645, 2018). "Recent study has shown that TRIM27-activated STAT3 to promote colitis and colitis-associated carcinogenesis." (PMID 31921311, 2019). "As a mediator of IL-6-induced STAT3 activation, TRIM27 plays important roles in DSS-induced colitis and AOM/DSS-induced CAC development." (PMID 30143645, 2018). "In the DSS-induced acute colitis model, Trim27−/− mice displayed attenuated colitis in comparison to their wild-type littermates." (PMID 30143645, 2018). "Deficiency of TRIM27 significantly impairs dextran sulfate sodium (DSS)-induced STAT3 activation, inflammatory cytokine expression and colitis as well as azoxymethane (AOM)/DSS-induced colitis-associated cancer in mice." (PMID 30143645, 2018). "Trim27 deficiency could decrease the levels of pro-inflammatory cytokines (IL-6, TNF-α, and IL-17A) in the colonic mucosa and suppress the DSS-induced colitis." (PMID 35565775, 2022). "Furthermore, deficiency of TRIM27 significantly impairs STAT3 activation, suppresses dextran sulfate sodium (DSS)-induced colitis, and azoxymethane (AOM)/DSS-induced CAC development in mice." (PMID 30143645, 2018). "In this study, we identified TRIM27 as an important mediator of STAT3 activation, which also plays a role in colitis and CAC development." (PMID 30143645, 2018). "Furthermore, TRIM27 expression was elevated in the colon tissues of Crohn’s patients and in CD4+T cells in the mesenteric lymph nodes of DSS-induced colitis mice." (PMID 34956195, 2021).
lung carcinoma (6 papers, 2020 to 2025). "SIX3 expression is associated with improved survival in lung cancer, whereas TRIM27 expression indicates a poor survival outcome based on a Kaplan-Meier Plotter database and our hospital cohort." (PMID 33264103, 2020). "TRIM27 expression is associated with poor prognosis of EGFR-mutated lung cancers, indicating that TRIM27 status may be related to anticancer therapy response in lung cancer with EGFR mutations." (PMID 33264103, 2020). "However, the underlying mechanism by which TRIM27 regulates lung cancer progression is not fully understood." (PMID 33264103, 2020). "Tripartite motif containing 27 (TRIM27) is highly expressed in lung cancer and plays an important role in cancer prognosis by encoding a member of the tripartite motif (TRIM) family." (PMID 33448640, 2020). "Although it is known that TRIM27 is upregulated in lung cancer tissues, and its silencing significantly inhibits lung cancer cell migration, adhesion, invasion, and proliferation, the underlying molecular mechanism is still not understood." (PMID 33264103, 2020). "Tripartite motif containing 27 (TRIM27) is highly expressed in lung cancer, including non‐small‐cell lung cancer (NSCLC)." (PMID 33448640, 2020). "TRIM27 has not been previously associated with clefting or craniofacial development but has been shown to be differentially methylated in prostate and lung cancers." (PMID 34055787, 2021). "This evidence strongly support our hypothesis and clarifies a relationship between SIX3 and TRIM27 in the pathogenesis of lung cancer." (PMID 33264103, 2020). "TRIM27 is associated with poor prognosis of lung cancer with EGFR mutations, and it has been reported to regulate migration, invasion, and proliferation of lung cancer cells." (PMID 33264103, 2020). "However, the prognostic import of either TRIM27 or SIX3 for lung cancer of different tumor stage or histology requires further investigation." (PMID 33264103, 2020). "Given the interplay between mRNA export and autophagy, the interaction of TRIM27, FYTTD1, SHISA9 and pack‐years of smoking may influence autophagy and, in turn, affect lung cancer prognosis." (PMID 39630602, 2025). "Thus, it is plausible that SHISA9 interacts with TRIM27, KIAA0226 and smoking, influencing the autophagy process and ultimately affecting lung cancer prognosis." (PMID 39630602, 2025). "We measured the expression of TRIM27 and SIX3 as well as investigated whether there was a correlation between them in lung cancer tissue samples." (PMID 33264103, 2020). "Among them, SMURF1, MDM2, SMURF2, TRIM27, and NEDD4L are involved in lung cancer progression." (PMID 33264103, 2020). "Importantly, SIX3 inhibited TRIM27-induced NSCLC cell proliferation and metastasis indicating the involvement of SIX3 in TRIM27-mediated tumorigenesis of lung cancer." (PMID 33264103, 2020). "Furthermore, we found that TRIM27 and SIX3 expression in lung cancer tissues is negatively correlated." (PMID 33264103, 2020). "In addition, TRIM27 and SIX3 expression in lung cancer tissues is negatively correlated." (PMID 33264103, 2020). "However, the exact mechanism how SIX3 and TRIM27 regulate S100P in lung cancer is not known, and thus, warrants further investigation." (PMID 33264103, 2020). "Similarly, the amount of protein of SMURF2 and TRIM27 was also increased and that of SIX3 was decreased in lung cancer tissues compared with adjacent normal lung tissues, although we found that there was a significant correlation between the protein level of SIX3 and TRIM27, but not of SMURF2." (PMID 33264103, 2020). "In addition, we found that TRIM27 is upregulated in lung cancer tissues compared with normal lung tissues in our cohort, which is consistent with that found in a previous study, and that higher TRIM27 expression correlates with lower SIX3 expression in lung cancer tissue samples from our cohort." (PMID 33264103, 2020).
colorectal cancer (5 papers, 2018 to 2023). A primary or metastatic malignant neoplasm that affects the colon or rectum. "Previous report has demonstrated that TRIM27 accelerates the progression of colorectal cancer." (PMID 31719796, 2019). "It was reported that TRIM27 promoted EMT through activation of p-Akt in colorectal cancer." (PMID 31921311, 2019). "Moreover, the oncogene TRIM27 has activated the phosphorylation of AKT in colorectal cancer cells." (PMID 32051827, 2020). "Moreover, TRIM27 has enhanced the phosphorylation of AKT pathway in colorectal cancer." (PMID 31719796, 2019).
esophageal squamous cell carcinoma (5 papers, 2019 to 2024). Esophageal squamous cell carcinoma (ESCC) is a type of esophageal carcinoma (EC) that can affect any part of the esophagus, but is usually located in the upper or middle third. "TRIM27 promotes proliferation, inhibits apoptosis, and enhances glucose uptake in esophageal squamous cell carcinoma (ESCC) cells." (PMID 38225560, 2024). "For instance, TRIM27 enhanced esophageal squamous cell carcinoma growth via activation of the AKT pathway." (PMID 33982666, 2021). "In addition, previous study reported that Trim27 could directly interact with PTEN to modulate apoptosis of esophageal squamous cell carcinoma (ESCC) and accelerate its glucose uptake by regulating PI3K/Akt signaling pathways." (PMID 35311628, 2022). "TRIM27 functions as a pro-proliferative factor, and participates in energy metabolism by activating the PI3K/AKT pathway in esophageal squamous cell carcinoma, and cell cycle arrest, and apoptosis in ovarian cancer and facilitates the invasion and metastasis of colorectal cancer." (PMID 36261847, 2022). "Nevertheless, the biological function of TRIM27 in esophageal squamous cell carcinoma (ESCC) is still not clear." (PMID 31719796, 2019).
lupus nephritis (5 papers, 2022 to 2025). Glomerulonephritis in the context of systemic lupus erythematosus. "Recent studies demonstrated that TRIM27 was involved in the injury of glomerular endothelial cells in lupus nephritis (LN) through the FoxO1 pathway and in IgA nephropathy (IgAN) via T cell signaling." (PMID 36627639, 2023). "At the same time, we also describe the roles of TRIM27 in other human diseases, such as lupus nephritis, ischemia-reperfusion injury and Parkinson’s disease." (PMID 36200036, 2022). "During the past decades, TRIM27 was reported to be involved in many diseases, including cancer, lupus nephritis, ischemia-reperfusion injury and Parkinson’s disease." (PMID 36200036, 2022). "It has been suggested that knockdown of TRIM27 inhibited the endothelial cells injuries in lupus nephritis via the FoxO1 signalling pathway." (PMID 37582060, 2022). "At the same time, another study reported that knockdown of TRIM27 could inhibit the proliferation of mesangial cells in lupus nephritis via the FoxO1 pathway." (PMID 36200036, 2022). "TRIM27 was reported to be highly expressed in the glomerular endothelial cells of patients with lupus nephritis, and TRIM27 knockdown could attenuate glomerular endothelial cell injury by regulating the FoxO1 signaling pathway." (PMID 36200036, 2022).